RBFA (ribosome binding factor A)
Synonyms: C18orf22; FLJ21172; HsT169
Tractability: Small molecule: a structure with a bound ligand is known. PROTAC: its protein half-life has been measured.
Gene: Protein-coding gene on chromosome 18 (80,034,389 to 80,050,651, forward strand). Ensembl gene ENSG00000101546.
Subcellular location: Mitochondrion
Subcellular location (Human Protein Atlas): Mitochondria
Gene Ontology:
Molecular function: protein binding; ribosomal small subunit binding; rRNA binding
Biological process: mitochondrial small ribosomal subunit assembly; rRNA processing
Cellular component: methyltransferase complex; mitochondrial matrix; mitochondrion
Genetic constraint (gnomAD): Loss-of-function variants: 11 observed, 18.64 expected, observed/expected ratio (o/e) 0.59, 90% interval 0.37 to 0.98. The upper end of that interval is the gene's LOEUF score, 0.98, which puts it in group 4 of 6, group 1 being the genes least tolerant of losing a copy. Missense variants: 401 observed, 389.83 expected, observed/expected ratio (o/e) 1.03, 90% interval 0.95 to 1.12. Synonymous variants: 170 observed, 170.34 expected, observed/expected ratio (o/e) 1, 90% interval 0.88 to 1.13.
Homologues: Orthologues: chimpanzee RBFA (99% identical), macaque RBFA (88% identical), guinea pig RBFA (64% identical), mouse Rbfa (60% identical), rat Rbfa (57% identical), dog RBFA (56% identical), tropical clawed frog rbfa (38% identical), zebrafish rbfa (33% identical), Drosophila melanogaster CG15916 (17% identical), Caenorhabditis elegans C25G4.3 (13% identical).
Diseases named in the same sentence as RBFA in open-access papers:
RBFA is named in the same sentence as 4 diseases in open-access papers, as found by Europe PMC text mining. Sharing a sentence is not in itself a finding about the gene and the disease. The quoted sentences say what the papers report.
autism spectrum disorder (1 paper, 2021). A spectrum of developmental disorders that includes autism, and Asperger syndrome. "RBFA—Copy number variation analysis identified RBFA (referred to as C18orf22), among several other genes, as a risk gene for autism spectrum disorder." (PMID 33917098, 2021).
metabolic syndrome (1 paper, 2025). A cluster of metabolic risk factors for CARDIOVASCULAR DISEASES and TYPE 2 DIABETES MELLITUS. "Of the 22 female-specific MDD/metabolic syndrome pleiotropic regions, possible causal risk loci mapped to multiple genes (GPC6, SHISA9, RP11-154H12.3, KCNG2, TXNL4A, RBFA and ADNP2)." (PMID 40858613, 2025).
cancer (1 paper, 2023). A tumor composed of atypical neoplastic, often pleomorphic cells that invade other tissues. "Overlap of essential E‐boxes for four cancer cell lines revealed only three (1%) common E‐boxes: chr1_BS1363_CACAATG with neighbor genes MECR and PTPRU, chr11_BS79_CGCGTG localized near RPLP2 and PIDD1, and chr18_BS691_CATGTG adjacent to RBFA and TXNL4A." (PMID 37519063, 2023).
infection (1 paper, 2009). The state of being infected such as from the introduction of a foreign agent such as serum, vaccine, antigenic substance or organism. "In the absence of RbfA, bIL66 M1 grew poorly at 18°C due to activation of abortive infection by low temperature." (PMID 19173723, 2009).